OR8B12 (olfactory receptor family 8 subfamily B member 12)
Description:
Odorant receptor.
Synonyms: OR11-317
Tractability: Small molecule: it belongs to a druggable protein family. Antibody: UniProt places it where antibodies can reach, with medium confidence; UniProt predicts a signal peptide or a membrane-spanning region; its Gene Ontology location is reachable by antibodies, with medium confidence.
Gene: Protein-coding gene on chromosome 11 (124,539,635 to 124,545,333, reverse strand). Ensembl gene ENSG00000170953.
Subcellular location: Cell membrane
Pathways (Reactome):
Sensory Perception: Expression and translocation of olfactory receptors
Gene Ontology:
Molecular function: olfactory receptor activity; G protein-coupled receptor activity
Biological process: G protein-coupled receptor signaling pathway; sensory perception of smell; detection of chemical stimulus involved in sensory perception of smell
Cellular component: plasma membrane; membrane
Genetic constraint (gnomAD): Loss-of-function variants: 2 observed, 1.48 expected, observed/expected ratio (o/e) 1.35, 90% interval 0.44 to 1.92. That is too few expected variants to judge how well the gene tolerates losing a copy. Missense variants: 382 observed, 395.37 expected, observed/expected ratio (o/e) 0.97, 90% interval 0.89 to 1.05. Synonymous variants: 151 observed, 156.44 expected, observed/expected ratio (o/e) 0.97, 90% interval 0.85 to 1.11.
Homologues: Orthologues: rat Or8b12 (86% identical), pig OR8B12 (85% identical), mouse Or8b12 (85% identical), rat Olr1198 (85% identical), mouse Or8b12b (84% identical), dog OR8B12 (84% identical), mouse Or8b12c (83% identical), rat Or8b12c (82% identical). Paralogues in human: OR8B8 (80% identical), OR8B2 (69% identical), OR8B3 (68% identical), OR8B4 (64% identical), OR8G1 (61% identical), OR8G5 (59% identical), OR8A1 (59% identical), OR8G3 (58% identical), OR8D1 (57% identical), OR8D2 (56% identical), OR8D4 (56% identical), OR8G2P (56% identical), and 84 more.
Diseases named in the same sentence as OR8B12 in open-access papers:
OR8B12 is named in the same sentence as 1 disease in open-access papers, as found by Europe PMC text mining. Sharing a sentence is not in itself a finding about the gene and the disease.
OR8B12 shares sentences with these, for which no sentence is quoted: schizophrenia 1 (1 paper).